VIP (vasoactive intestinal peptide)
Diseases named in the same sentence as VIP in open-access papers (continued):
Sharing a sentence is not in itself a finding about the gene and the disease.
prostate carcinoma (10 papers, 2011 to 2023). A carcinoma that arises from epithelial cells of the prostate gland. "Taken together, these observations strongly support the notion that VIP plays an important role in breast and prostate cancer pathogenesis and suggests that elevated concentrations of VIP in the circulation may represent a risk factor for these cancer types." (PMID 22140573, 2011). "VIP behaves as a pro-metastatic factor in prostate cancer, whereas a protector in hepatocellular carcinoma dependent on cAMP/Bcl-xL pathway induced apoptosis." (PMID 36890467, 2023). "VIP regulates VEGF expression in prostate cancer by targeting the cAMP/Epac/ERK/PI3K signaling pathway." (PMID 35910387, 2022). "For example, activation of calcitonin and vasoactive intestinal polypeptide (VIP) receptors have been shown to support androgen-independent growth of prostate cancer cells." (PMID 30871232, 2019). "A similar approach is being investigated for a number of tumors overexpressing VPAC1 (mainly breast and prostate cancer) using various radiolabeled VIP analogs." (PMID 29674997, 2018). "Similarly to NE, VIP is secreted by autonomic nerves in the prostate gland and also can be produced by prostate cancer cells." (PMID 30871232, 2019). "VIP has been shown to play a role in the pathogenesis of breast and prostate cancer." (PMID 25547487, 2014). "There also is mounting evidence that VIP is involved in the pathogenesis of prostate cancer." (PMID 22140573, 2011). "Also, vasoactive intestinal peptide has been reported to induce neuroendocrine differentiation in the LNCaP prostate cancer cells and the orexin type 1 receptor is overexpressed in advanced prostate cancer with a neuroendocrine differentiation." (PMID 33572108, 2021). "Herein we suggest a role for naturally produced antibodies reactive with the vasoactive intestinal peptide (VIP) in the suppression of breast and prostate cancer, which we believe could offer a possible molecular mechanism underlying control of these cancers by physical exercise." (PMID 22140573, 2011). "Vasoactive intestinal peptide (VIP) promotes angiogenesis, invasion, and metastasis in prostate cancer by regulating the expression of VEGF and COX-2, both of which are related to the activation of NF-κB." (PMID 35910387, 2022). "VIP antagonists suppress the release of prostate-specific antigen (PSA) and inhibit growth of breast and prostate cancer cells." (PMID 22140573, 2011). "VIP increases neuroendocrine differentiation and stimulates interleukin-6 production and prostate-specific antigen (PSA) secretion in prostate cancer." (PMID 22140573, 2011). "Thus, our results show that VIP provides another layer of drug resistance by inducing activation of PKA in CSCs of breast and prostate cancer." (PMID 28569785, 2017). "In line with this hypothesis is that physical activity provides a potential source of the natural anti-VIP/NTM antibodies that could contribute to the control of breast and prostate cancer." (PMID 22140573, 2011). "We found that sera from individuals having breast and prostate cancers have decreased titers of VIP natural antibodies as demonstrated by a lower reactivity against peptide NTM1, having similar informational and structural properties as VIP." (PMID 22140573, 2011). "In addition, VIP stimulates HER2 transphosphorylation in androgen-independent prostate cancer cells, stimulates their invasive capacity and contributes to prostate cancer pathogenesis by induction of malignant transformation." (PMID 22140573, 2011). "Herein we suggest a possible role for naturally produced antibodies reacting with peptides VIP and NTM1 in the control of breast and prostate cancer, which we believe could offer a possible molecular mechanism underlying positive effects of physical exercise in these cancers." (PMID 22140573, 2011).
prostate carcinoma (continued). "The level of circulating VIP is controlled by natural anti-VIP antibodies and we hypothesized that these suppressive antibodies could contribute to a better control of breast and prostate cancer and that lack of these antibodies could contribute to the progression of these diseases." (PMID 22140573, 2011).
Hyperglycemia (9 papers, 2013 to 2025). An increased concentration of glucose in the blood. "Although Tβ4 and VIP have been investigated as monotherapies in the eye, it is unknown whether the two molecules can work synergistically to further improve the pathogenic hyperglycemia-induced effects on corneal epithelial cells." (PMID 37998149, 2023). "Our complementary approach provides a foundation for the therapeutic effects of Tβ4/VIP regarding hyperglycemia-induced changes in corneal epithelial cell behavior, barrier integrity, and wound healing mechanisms." (PMID 37998149, 2023). "VIP-induced glucagon secretion occurs during hypoglycemia, while VIP exerts its role of promoting insulin secretion during hyperglycemia." (PMID 36204104, 2022). "During hyperglycaemia conditions, a clearly visible increase in VIP expression was observed in all investigated areas of the small intestine." (PMID 30987291, 2019). "Moreover, a series of studies revealed that VIP was involved in various biological activities, such as hormonal regulation, hyperglycemia, inflammatory response, and systemic vasodilation." (PMID 36499231, 2022). "While increasing VIP and GAL immunoreactivity, molecules showed neuroprotective and pro-inflammatory properties, confirming that hyperglycemia leads to inflammatory conditions and damages autonomic neuronal cells." (PMID 32192078, 2020).
multiple sclerosis (9 papers, 2012 to 2025). A progressive autoimmune disorder affecting the central nervous system resulting in demyelination. "While VIP may present a dual function in the regulation of multiple sclerosis, it should be borne in mind that ADNP regulation, while in part associated with VIP and PACAP, is regulated by other control mechanisms." (PMID 23162535, 2012). "Targeting VIP and PACAP receptor signalling is considered as a new approach against multiple sclerosis." (PMID 35203615, 2022). "There are examples of people who produce abzymes with potentially clinically significant effects, for example, DNA, immunoglobulin, vasoactive intestinal peptide (VIP), myelin basic protein (MBP) in persons with multiple sclerosis, and factors in the coagulation cascade (39, –, 41)." (PMID 40693778, 2025).
rosacea (9 papers, 2016 to 2025). A chronic erythematous skin disorder that affects the face. "In a mouse model recapitulating a recurrent Lrrc4 mutation from human patients, we find rosacea-like skin inflammation, underpinned by excessive vasoactive intestinal peptide (VIP) release by peripheral neurons." (PMID 37402769, 2023). "Most importantly, our results demonstrated that in an LL37-induced rosacea mouse model, mutation in Lrrc4 facilitates rosacea-like skin inflammation by neuropeptide VIP derived from peripheral neurons." (PMID 37402769, 2023). "It has demonstrated efficacy in addressing persistent erythema and flushing associated with rosacea by inhibiting mast cell degranulation and acetylcholine release, while also modulating substance P, calcitonin gene‐related peptide, and vasoactive intestinal peptide." (PMID 39248245, 2024). "We speculated that the expression of VIP induced by amino acids could be an important cause of neurogenic vasodilation in rosacea." (PMID 36219476, 2022). "It is reported that expression of the receptor of VIP is positive in slice biopsies from patients with rosacea compared with controls." (PMID 36219476, 2022). "This leads to increased release of neuropeptides such as pituitary adenylate cyclase-activating polypeptide (PACAP), vasoactive intestinal peptide (VIP), VEGF, adrenomedullin, calcitonin gene-related peptide (CGRP), and substance P (SP), all implicated in rosacea pathogenesis." (PMID 39351216, 2024). "By utilizing an antagonist peptide of VIP receptor, VIPhyb34,35, we found that inhibition of VIP signaling could greatly improve rosacea-like dermatitis in Lrrc4 mutant mice compared with the mice treated with scrambled VIPhyp peptides (sVIPhyp)." (PMID 37402769, 2023). "In addition, some neuropeptides, such as CGRP, PACAP, VIP, and substance P, have properties that are closely related with the pathogenesis of rosacea and are increased in that condition." (PMID 33800730, 2021). "In addition, various neuropeptides, such as pituitary adenylate cyclase-activating polypeptide (PACAP), vasoactive intestinal peptide, calcitonin gene-related peptide (CGRP), and substance P, are expressed at elevated levels in rosacea patients." (PMID 39044833, 2024). "For example, the expressions of neuromediators such as pituitary adenylate cyclase-activating polypeptide (PACAP), vasoactive intestinal peptide (VIP), adrenomedullin, calcitonin gene-related peptide (CGRP), and substance P were found to be enhanced in rosacea." (PMID 27649161, 2016).
schizophrenia (9 papers, 2015 to 2025). A major psychotic disorder characterized by abnormalities in the perception or expression of reality. "Accordingly, mice modeling the schizophrenia-predisposing 22q11.2 deletion syndrome with known SWM learning deficits recapitulated this aberrant VIP interneuron activity profile and showed reduced vHPC targeting of mPFC VIP interneurons." (PMID 40777258, 2025). "We had previously found that developmental perturbation of VIP interneurons by conditional deletion of the schizophrenia-associated gene ErbB4 caused a similar loss of state-dependent cortical regulation." (PMID 32343226, 2020). "Schizophrenia models reveal that altered VIP interneuron function affects pyramidal neuron activity and prefrontal cortex processing, potentially leading to symptoms such as hypofrontality." (PMID 39916937, 2024). "Altered nicotinic receptor function in VIP+ cells led to suppressed pyramidal neuron activity and schizophrenia-like hypofrontality." (PMID 39916937, 2024). "VIP+ cell-mediated inhibition of SST+ cells was impaired in a mouse model carrying a human polymorphism in the α5 nicotinic receptor subunit, associated with nicotine addiction and schizophrenia." (PMID 39916937, 2024). "There is evidence that some patients with schizophrenia do have reduced calbindin expression and a disordered pattern of calbindin interneurons in the hippocampus [99, 100, but see 101], while the VIP-positive interneurons that express mGlu7 remain unaffected in schizophrenia." (PMID 32533466, 2020). "The impetus for our studies were the series of reports showing that micro-multiplications of the VIPR2 gene is associated with schizophrenia and ASD, and that these mutations were associated in patients with heightened VIP-induced cAMP responsiveness." (PMID 32581681, 2020). "Additionally, a copy number gain in the PACAP gene due to a partial trisomy has been shown to cause severe mental retardation, and multiplication of the gene for VPAC2, a common VIP and PACAP receptor, is associated with schizophrenia." (PMID 25807538, 2015). "The vasoactive intestinal peptide (VIP) of parasympathetic origin may contribute to clozapine (muscarinic M1-receptor)-induced sialorrhea, an adverse effect created by its synergistic interaction with the antipsychotic in some patients with schizophrenia." (PMID 32373066, 2020). "Thus, modulating VIP+ and/or SST+ interneuron activity holds therapeutic potential for addressing GABAergic hypofunction in schizophrenia." (PMID 39916937, 2024). "Its loss (in schizophrenia and PCP-Iso) would be expected to reduce interneuron firing and potentially prevent further 5-HT6 antagonist-mediated disinhibition, without impacting on responses of VIP-expressing interneurons to mGlu7 antagonism." (PMID 32533466, 2020). "Future studies should also assess the integrity of VIP-expressing interneurons in PCP-Iso to test our current working hypothesis that cells mediating the effects of mGlu7 receptor ligands would be spared in this animal model and therefore mirror findings in patients with schizophrenia." (PMID 32533466, 2020).
Crohn disease (8 papers, 2013 to 2024). A gastrointestinal disorder characterized by chronic inflammation involving all layers of the intestinal wall, noncaseating granulomas affecting the intestinal wall and regional lymph nodes, and transmural fibrosis. "This approach has been successfully applied to uncover many disease-related pathways, such as the IL12/IL23 pathway associated with Crohn’s disease, the Vasoactive Intestinal Peptide (VIP) pathway important for Obesity, as well as the WNT-signaling pathway in Type2 diabetes(T2D)." (PMID 26308950, 2015). "For example, in people suffering from Crohn’s disease, an increase in the population of VIP-LI nervous structures has been noted, while ulcerative colitis in children caused a decrease in the number of intramucosal VIP-LI nerve fibers in the colon." (PMID 32998326, 2020). "Likewise, upregulated expression of VIP in the ENS structures was noted during inflammatory states in the GI tract, such as Helicobacter pylori infection, Crohn’s disease, and ulcerative colitis." (PMID 33353157, 2020).
irritable bowel syndrome (8 papers, 2014 to 2023). Irritable bowel syndrome (IBS) is a chronic functional condition of the lower gastrointestinal (GI) tract characterized by abdominal pain or discomfort and disordered bowel habit (diarrhea, constipation, or fluctuation between the two). "However, the serum levels of 5-HT, SP and VIP were significantly increased in rats with irritable bowel syndrome." (PMID 38163069, 2023). "Neuropeptide Y (NPY) and vasoactive intestinal peptide (VIP) are two forms of neurotransmitter that play an important role in the pathogenesis of abnormalities in the brain-gut axis in irritable bowel syndrome (IBS)." (PMID 34211567, 2021). "The secretion of substance P (SP) and vasoactive intestinal polypeptide (VIP) are decreased, motilin and cholecystokinin (CCK) are increased after treatment with electrical acupuncture (EA) in rats with irritable bowel syndrome (IBS)." (PMID 32631387, 2020).
melanoma (8 papers, 2018 to 2026). A malignant, usually aggressive tumor composed of atypical, neoplastic melanocytes. "In solid tumors, human gene expression data shows VIP expression to greatly vary between different tumors, with highest levels in pancreatic exocrine cancers and lowest in melanoma." (PMID 30400835, 2018). "However, further studies are needed in order to explore in detail the impact of VIP on melanoma cells." (PMID 34068618, 2021). "Its effect in melanoma cells could be of interest since VIP has been suggested to be involved in skin inflammation and modulation of skin immune responses." (PMID 34068618, 2021). "This evidence could strengthen the search for a therapy in the direction of drugs already used in this setting as showed with the successful adoption of synthetic vasoactive intestinal peptide in a melanoma patient with CIP." (PMID 33302981, 2020). "Vasoactive intestinal peptide (VIP) plays a multifaceted role in cancer biology, yet its prognostic and immunological implications in melanoma remain underexplored." (PMID 42216340, 2026). "On the other hand, supernatants from murine melanoma cell lines B16F10 and D4M had low to undetectable VIP." (PMID 36302761, 2022). "In melanoma patients, the median transcript levels of genes expressed in sensory nerves [Nav1.8, TRPV1 and vasoactive intestinal peptide (VIP)] were used to stratify 21437 patient tumour transcriptomes into high and low expression for each gene." (PMID 32691511, 2020). "In addition, VIP increases ACTH levels in neonate rats and induces melanin synthesis via up‐regulation of CREB, MITF and Tyr in murine melanoma cell lines (B16F10;)." (PMID 39910963, 2025).
Obesity (8 papers, 2012 to 2025). Accumulation of substantial excess body fat. "The VIP pathway genes have been strongly correlated to the development of adiposity and obesity by a genome-wide association analysis of 500,000 SNPs from 1000 United States citizens." (PMID 37508442, 2023). "The PACAP and VIP pathways have been linked to the regulation of body weight and fat mass accumulation, and to the development of obesity and metabolic syndrome." (PMID 37508442, 2023). "A GWA analysis in 1,000 participants found that the vasoactive intestinal peptide (VIP) pathway was strongly associated with fat mass and with BMI, suggesting that the VIP pathway may play an important role in the development of obesity." (PMID 29016858, 2017). "Overall, these findings suggest that the VIP effects on body fat mass accumulation and obesity development are mediated through the VPAC2 pathway." (PMID 37508442, 2023). "This review demonstrates that the PACAP and VIP pathways are important targets and should be considered in the treatment of overeating and obesity disorders, as well as metabolic syndrome." (PMID 37508442, 2023). "In this review, the major physiological and metabolic actions of PACAP and VIP through their specific receptors are summarized, and the most recent advances in understanding the role of PACAP and VIP in the pathogenesis of metabolic diseases and obesity disorders are described." (PMID 37508442, 2023). "Previously, we assessed the overall physiologic functions of endogenous VIP on body phenotype and metabolism and suggested that alteration of the VIP pathways could be involved in the development of obesity and metabolic syndrome." (PMID 35336804, 2022). "Overall, our study showed that endogenous VIP is a key regulator of appetite, feeding behavior, body phenotype, and plasma metabolic hormone levels, thus supporting a potential role for the VIP pathways in the development of obesity and metabolic syndrome." (PMID 35336804, 2022).
psoriasis (8 papers, 2009 to 2023). An autoimmune condition characterized by red, well-delineated plaques with silvery scales that are usually on the extensor surfaces and scalp. "Vasoactive intestinal peptide (VIP) is another neuropeptide strongly associated with psoriasis." (PMID 32252279, 2020). "We provide the first evidence of the association between low serum VIP levels and increased disease severity in patients with early SpA, namely, impaired functional status, bone edema in MRI, and a more intense inflammatory burden (anemia, psoriasis, IBD, and enthesitis)." (PMID 25711477, 2015). "Vasoactive intestinal peptide (VIP)-positive nerve fibers in the dermis, dermal-epidermal junction, and epidermis are higher in patients with psoriasis than in undamaged and healthy skin." (PMID 36405690, 2022). "Previous findings in psoriasis appear more homogeneous and point to higher serum VIP levels in patients with psoriasis." (PMID 35955723, 2022). "A dysfunctional expression and/or distribution of a great number of neuropeptides (e.g., substance P, somatostatin, vasoactive intestinal peptide) has been demonstrated in psoriasis." (PMID 27455241, 2016). "The association between low serum VIP levels and extra-articular features of SpA, such as psoriasis and enthesitis, further suggests the role of VIP as a biomarker of severity, since both impair quality of life and increase treatment requirements." (PMID 25711477, 2015). "Elevated expression of VIP in the plaques and plasma of psoriasis patients have been reported." (PMID 35955723, 2022).